NBPF7P (NBPF member 7, pseudogene)
Synonyms: formerly NBPF7
Gene: Transcribed unprocessed pseudogene on chromosome 1 (119,834,870 to 119,844,514, reverse strand). Ensembl gene ENSG00000215864.
Subcellular location: Cytoplasm